TFAP2A (transcription factor AP-2 alpha)
Diseases named in the same sentence as TFAP2A in open-access papers (continued):
Sharing a sentence is not in itself a finding about the gene and the disease.
cancer (continued). "It was noteworthy that TFAP2A might be involved in epigenetic modifications regulating, such as mentioned DNA and histone methylation, which were imbalanced in many cancers and could be considered for further investigation." (PMID 38265973, 2024). "The genetic alteration of TFAP2A in various cancers was then investigated by cBioPortal." (PMID 38265973, 2024). "We utilized the ESTIMATE Score to evaluate TFAP2A expression in 16 cancers TME." (PMID 38265973, 2024). "Among them, high TFAP2A expression meant significantly worse prognosis with a few exceptions, which was supported by other studies and proved that TFAP2A perhaps could be a useful pan-cancer prognosis biomarker." (PMID 38265973, 2024). "Then, we found TFAP2A expression related to immune subtypes, C1-C6, in one-half of 16 cancer types." (PMID 38265973, 2024). "In addition to expressing a unique KRT profile, the basal cancers with squamous differentiation also express the transcription factor P63 and TFAP2A." (PMID 36293167, 2022). "Aberrant expressions of TFAP2A have been reported in various cancers." (PMID 35494004, 2022). "We have offered a relatively more objective and comprehensive assessment about clinical significance of TFAP2A upon LUAD, so we deduced that, collectively, TFAP2A could play a cancer-promoting role in LUAD malignant progression." (PMID 33824285, 2021). "In addition, Dimitrova found that the expression of TFAP2A is increased in more “stem-like” cancers." (PMID 33713277, 2021). "The aberrant expression of TFAP2A has been reported in different cancers." (PMID 33713277, 2021). "Simultaneously, it has been demonstrated that TFAP2A could influence the transcription of target genes involved in many different types of cancer." (PMID 33493131, 2021). "Additionally, activating enhancer binding protein 2 alpha (TFAP2A) plays a critical role in tumorigenesis, tumor invasion, and metastasis of many cancers including breast cancer, melanoma, and glioma." (PMID 33273928, 2020). "Moreover, IGF1R, TNPO1 and FASN are experimentally validated targets for TFAP2A, as annotated by RegNetwork software, and are involved in multiple cancer stemness and drug resistance processes." (PMID 30944375, 2019). "Aberrant expression of TFAP2A has been observed in various cancers." (PMID 28412966, 2017). "We found that upon induction of EMT, the activity of TFAP2A, reflected in the expression level of its predicted targets, is up-regulated in a variety of systems, both murine and human, while TFAP2A’s expression is increased in more “stem-like” cancers." (PMID 28412966, 2017). "Among the set of genes that we identify as being related to RCC, some were known from previous studies (e.g. ATP6V1B1, EGLN3, SLC25A5, TUBB, ALDOA); others had never before been associated with RCC, but have been identified with other cancers (e.g. ABL2, JAZF1, TFAP2A)." (PMID 19455236, 2007). "Finally, we did not analyze and elucidate the potential role of TFAP2A in cancer-associated biological processes other than immune regulation, such as DNA and histone methylation." (PMID 38265973, 2024). "TFAP2A and TFAP2C are two members of the AP-2 family of TFs that play important roles in cancer development, but also in early embryonic development, especially of the neural crest and trophectoderm, where they have both redundant and non-redundant functions." (PMID 39853537, 2025). "TFAP2A modulates key oncogenes, including EGFR, and contributes to therapy resistance by promoting epithelial-mesenchymal transition (EMT) and cancer stem cell properties." (PMID 41323280, 2025). "Among the TFAP2 family members, TFAP2A, TFAP2B, and TFAP2E interact with β-catenin to inhibit or promote oncogenesis in different types of cancers." (PMID 40837414, 2025). "The formation of this stable complex disrupts the interaction between transcription factor AP‐2 alpha (TFAP2A) and ATF4‐G4, resulting in a substantial reduction in intracellular ATF4 levels and the eventual death of cancer cells." (PMID 38994891, 2024).
cancer (continued). "Inhibition of TFAP2A reduced ATF4 expression and suppressed cancer cell proliferation in the presence of 0.25 mM glutamine." (PMID 38994891, 2024). "Compared with adjacent tissues, the expression of TFAP2A, TFAPB, TFAP2D and TFAP2E in cancer tissue was significantly increased." (PMID 37859819, 2023). "Similar to TFAP2A, the TFAP2C gene was mainly overexpressed among various cancers and this observation is true for both LUAD and LUSC subtypes (p < 0.001)." (PMID 36831334, 2023). "Small ubiquitin-like modifier (SUMO)-conjugated TFAP2A transcription factor induces the expression of CD44, which maintain the cancer stemness characteristics of breast and colorectal CSCs30." (PMID 30944375, 2019). "To investigate the expression status of TFAP2A and SIX1 proteins in benign and malignant lung tissue, we performed IHC staining of 7 lung tumor samples and 7 adjacent non-cancer tissue samples." (PMID 30177858, 2018). "Seven cofactors (TFAP2A, E2F, GSTM1, IL6, PATZ1, MEF2A and GTF2I) identified in two of the five cancer types have general functions in cancers." (PMID 28684851, 2017). "Further, they conclude that the interaction between TFAP2A and ZEB2 promoter affects ZEB2 expression, hence modulating the EMT process itself and providing evidence for a role of TFAP2A in cancer progression." (PMID 28412966, 2017). "ChIP‐Seq and ChIP‐qPCR analysis allowed us to identify a subset of hypoxia‐regulated genes that are co‐occupied by both TFAP2A and HIF‐1α, both in HeLa and MCF7 cancer cell lines, providing evidence that binding of TFAP2A to HIF‐inducible promoters is not a cell type‐specific event." (PMID 39994865, 2025). "TFAP2A and TFAP2B also exhibit repressive effects on cancer stemness." (PMID 37291585, 2023). "Upregulated TFAP2A and TFAP2C tend to be observed more frequently in “stem-like” cancers." (PMID 37291585, 2023). "We found that TFAP2A knockdown could influence EMT and decrease the cancer cells' migration in LUAD." (PMID 32015686, 2020). "However, the inhibition of TFAP2A SUMOylation under hypoxic condition can improve the transcriptional activity of HIF-1α and promote cancer cell survival." (PMID 33273928, 2020). "Further, miR-200b could target transcription factors, AP-2 alpha (TFAP2A), and MAPK7, which, in turn, inhibit the expression of TGF-β, impair TGF-β-induced EMT and decrease cancer cell proliferation in vitro." (PMID 29084594, 2017). "As both TFAP2A and HIF‐1 play critical roles in cancer progression, a detailed characterization of their crosstalk could lead to novel therapeutic strategies for targeting and killing cancer cells in hypoxic tumors." (PMID 39994865, 2025). "It has been reported that TFAP2A can play negative or positive roles in cancer cell proliferation." (PMID 36707053, 2023). "The observed overexpression in most cancer types, including LUAD and LUSC, may suggest rather oncogenic potential of these gene family members, and this finding is most highlighted in the case of TFAP2A and TFAP2C genes through both TIMER and GEPIA databases." (PMID 36831334, 2023). "However, it is important to point out that both TFAP2A and TFAP2C have been reported to have dual roles in carcinogenesis, i.e. either inhibitory or promoting depending on the specific tissues and stages of cancer progression." (PMID 24023917, 2013). "However, the roles of TFAP2A in liver metastasis in cancers have not been explored." (PMID 40727938, 2025).
cancer (continued). "Moreover, AP-2 family members regulate metabolic processes through their downstream targets, with TFAP2A shown to increase EZH2 expression by perturbing the activity of the nucleosome remodeling complex, contributing to the metabolic rewiring characteristic of cancer cells." (PMID 41373739, 2025). "Finally, the present study found that the TFAP2A gene was differentially hypomethylated in heavy smokers compared to controls in the analysis of noncancer subjects but not for the subset of cancer-diagnosed subjects." (PMID 37509437, 2023). "Only SLC7A11, TFAP2A, and LIMS2 are commonly regulated by the MDF in carcinomas (not in GBM), but only if the direction of the correlation was inversed for PAAC, whose impact on OS was also inverse." (PMID 32806596, 2020).
infection (6 papers, 2021 to 2025). The state of being infected such as from the introduction of a foreign agent such as serum, vaccine, antigenic substance or organism. "Our results indicate that TFAP2A significantly reduces Ydsphk1 promoter activity, suggesting that this regulatory mechanism may serve as a critical checkpoint in immune responses, modulating Ydsphk1 expression during the early stages of infection." (PMID 39769404, 2024). "We successfully established stable cell models of TFAP2A knock-down and overexpression in two LUAD cell lines (PC-9 and H1650) by recombinant lentiviruses infection." (PMID 33824285, 2021). "Other TFs in the network (e.g., PPARG, TFAP2A, ZNF143) may modulate expression for homeostasis or fine-tune the response depending on infection stage." (PMID 41408150, 2025).
adenocarcinoma (3 papers, 2018 to 2023). A common cancer characterized by the presence of malignant glandular cells. "Expression levels of TFAP2A and TFAP2C are higher in both adenocarcinoma and squamous cell lung cancer tissues than in normal lung tissues, and AP2 overexpression is associated with tumorigenesis and aggressive biology in lung cancer." (PMID 36123698, 2022).
neurodegenerative disease (2 papers, 2024 to 2025). A disorder of the central nervous system characterized by gradual and progressive loss of neural tissue and neurologic function. "TFAP2A affects neuronal function and survival and may play a role in the pathogenesis of neurodegenerative diseases." (PMID 39840278, 2024).
cardiac diseases (1 paper, 2024). "Currently, there are still too few studies on Tfap2a in cardiac diseases." (PMID 38402404, 2024).
neurodevelopmental disorder (1 paper, 2020). A behavioral and cognitive disorder with onset during the developmental period that involves impaired or aberrant development of intellectual, motor, or social functions. "The roles of the TFAP2A and HINFP have not yet been described in other neurodevelopmental disorders." (PMID 33080834, 2020).
peripheral neuropathy (1 paper, 2019). A disorder affecting the peripheral nervous system. "Mice with a Dhh::Cre-dependent deletion of both Tfap2a and Ep400, in contrast, exhibited an unsteady gait and impaired motor coordination as symptoms of a peripheral neuropathy." (PMID 31142747, 2019).
psychiatric disorder (1 paper, 2023). A disorder characterized by behavioral and/or psychological abnormalities, often accompanied by physical symptoms. "We have found GATA2, FOXC1 and TFAP2A among highly expressed TFs that are associated with DEGs are shared between PD and psychiatric disorders." (PMID 37654790, 2023).
TFAP2A also shares sentences with these, for which no sentence is quoted: Anophthalmia (4 papers); cataract (3); cervical cancer (3); glioblastoma (3); acute myeloid leukaemia (2); diabetes (2); esophageal cancer (2); Intellectual disability (2); iron deficiency (2); renal fibrosis (2); aniridia (1); aphakia (1); Auriculocondylar Syndrome 1 (1); autism (1); bile duct cancer (1); bladder urothelial carcinoma (1); Blepharocheilodontic syndrome 2 (1); cerebellar ataxia (1); cholesteatoma (1); Chorioretinal coloboma (1); cleft palate (1); congenital heart disease (1); COVID-19 (1); craniosynostosis (1); delirium (1); dementia (1); embryonal carcinoma (1); Friedreich ataxia (1); frontonasal dysplasia (1); gastric adenocarcinoma (1).
A further 38 diseases each share a sentence with TFAP2A in 1 paper.